CDX2 (caudal type homeobox 2)
Diseases named in the same sentence as CDX2 in open-access papers (continued):
Sharing a sentence is not in itself a finding about the gene and the disease.
tumor (continued). "RFS was significantly associated with LNM, general tumor type, histology grade, LVI, stroma type, tumor bud count, tumor bud cell mitosis, and CDX2 expression status." (PMID 36186777, 2022). "In a mouse model of colorectal carcinogenesis in vivo, BRAF V600E mutations in intestinal stem cells promote differentiation and require inactivation of SMAD4 or of intestinal differentiation transcription factor CDX2 for efficient tumor formation." (PMID 36079062, 2022). "The transcription factor that is particular to the intestines CDX2 plays a vital role in maintaining the normal function of the colonic epithelium and has been demonstrated to be a tumor suppressor." (PMID 36277982, 2022). "The depletion of CDX2 antagonized the synergistic effects of the drug combination on tumor inhibition." (PMID 35449124, 2022). "The expression level of CDX2 was considerably lower in the tumor tissue than in the normal tissue in all 10 cases." (PMID 35535692, 2022). "Three patients with reduced CDX2 expression had poorly differentiated tumours compared with 29 patients with high CDX2 expression (42.9 and 16.0%, respectively, p = 0.003)." (PMID 35027037, 2022). "In human CRC specimens, the downregulation of Cdx2 expression is indicative of more aggressive disease, while Cdx1:Cdx2:APCMin mice are inclined to develop highly invasive, villus neoplasms with reduced ephrin-B1 expression." (PMID 35269901, 2022). "This is illustrated in our recently published study, where we describe the interplay between the MMR status, tumor grade, and expression of cell maturation marker CDX2 (caudal type homeobox 2)." (PMID 36110945, 2022). "Our previous study revealed the regulatory effect of FXR on caudal-related homeobox transcription factor 2 (CDX2), a tumor suppressor, although the precise mechanism is unclear." (PMID 35449124, 2022). "Of the various CRC‐related genes, our results showed that CDX2 expression was severely decreased in tumor tissues compared with that in normal tissues." (PMID 35535692, 2022). "Kaplan–Meier analysis showed that patients with low levels of CDX2 expression in tumour had shorter overall survival (OS) and recurrence-free survival (RFS) than those with high levels." (PMID 33239678, 2021). "Taken together, this work demonstrates the strong oncogenic potential of the homeobox gene CDX2 in the hematopoietic lineage, in contrast with its physiological tumor suppressor activity exerted in the gut." (PMID 33960108, 2021). "SATB-2, ORP-1, MYB, and CDX-2 were related to cetuximab sensitivity as well as enhanced tumor immune cell infiltration in patients with CRC." (PMID 33632198, 2021). "As expected, the tumour volume and weight were significantly increased when CDX2 was knocked down, both of which effects were remarkably decreased after restoration of CXCL14." (PMID 33733587, 2021). "We observed significant correlations between the expression levels of the core DEGs SATB-2, ORP-1, MYB, and CDX-2 and tumor immune cell infiltration represented by the expression of B cell, CD4+ T cell, CD8+ T cell, and macrophage markers in TCGA." (PMID 33632198, 2021). "Another interesting observation of our study is the dependence of the prognostic impact of CDX2 to tumour localisation." (PMID 34616012, 2021). "The gastric metaplasia cells treated with CDCA induce the direct interaction of FXR to SHP, which increased the expression of CDX2 that acts as a tumour suppressor protein." (PMID 35006466, 2021). "Immunohistochemicaly, the tumor cells were positive for Cytokeratin (CK) 19, Cytokeratin (CK) 7, and homebox protein (CDX-2), which are highly sensitive markers of pancreatobiliar cancer." (PMID 33572607, 2021). "Forty-seven (5%) CRCs showed a nuclear expression in 61–89% of tumour cells and 90 carcinomas (9%) showed a reduced CDX2 staining within the range of 1–60% positive tumour cells." (PMID 34616012, 2021).
tumor (continued). "Despite this loss, high-grade tumours exhibit an enrichment for FOXA1, HOXB13 and CDX2 transcription factor binding sites, indicating a shared trans-regulatory programme." (PMID 34911933, 2021). "EFNA1 inhibits the proliferation of tumor cells in NSCLC by increasing the expression of tumor suppressor gene cdx-2." (PMID 34399788, 2021). "Results indicated that the number of infiltrated NK cells in SCC‐25 tumour spheroids was significantly increased after CDX2 overexpression, but was notably decreased after CDX2‐1 knockdown." (PMID 33733587, 2021). "The Transwell 2D invasion assays revealed CDX2 knockdown enhanced tumor cell invasion in the context of LIN28B overexpression." (PMID 33755595, 2021). "Emerging evidence supports a crucial role for CDX2 as a tumour suppressor in colorectal tumorigenesis." (PMID 33239678, 2021). "Our results extend these observations and suggest that these effects of Cdx2 on tumor phenotype are mediated through Notch function and downstream targets such as EphrinB1." (PMID 33525395, 2021). "The Cdx2 knockdown cells also formed significantly more and larger colonies relative to controls, consistent with a tumor-suppressive function of Cdx2 in this cell line." (PMID 33525395, 2021). "The Cdx2-ERT2Cre;Apcfl/fl;Atg5fl/fl showed a significant reduction in tumor number and burden compared with Cdx2-ERT2Cre;Apcfl/fl mice." (PMID 34138755, 2021). "Our findings argue towards the fact that not only the specific histologic subtype of CRC but also the tumour localisation and the microsatellite status have to be considered when the CDX2 status is assessed in order to determine patient prognosis." (PMID 34616012, 2021). "Consistently with its presumed key role in ITACs intestinal differentiation, CDX2 was overexpressed in all tumor samples." (PMID 34563241, 2021). "In an in vivo model of colon cancer, it was shown that miR-24-3p induced resistance to this drug, favoring tumor growth under treatment of methotrexate by down-regulating the CDX2/HEPH axis." (PMID 34912797, 2021). "No relevant difference was noted among the two etiologically different tumour groups concerning cumulative intestinal marker expression (p=0.556); however, the percentage of cases with CDX2 expression turned out to be significantly lower (p=0.007) in CrD-SBCs." (PMID 33963925, 2021). "If not enough, it can also induce EMT, antagonize apoptosis in vitro of breast cancer cells and promote tumor growth in nude mice xenografted with MCF-7 cells via downregulation of the transcription factors CDX2 and HOXA5." (PMID 34912797, 2021). "In summary, CDX2 is likely to be an important biomarker for guiding evaluation of tumour progression and prognosis." (PMID 33239678, 2021). "The expression of CDX2 in adults is restricted to the gastrointestinal tract and delineates a putative tumor-suppressor and prognostic marker in colorectal cancer." (PMID 34067172, 2021). "In the present study, over-expressed CDX2 and let-7b inhibited lymph node metastasis and tumor growth by silencing COL11A1." (PMID 31938021, 2020). "Strong and diffuse nuclear staining of CDX2+ was observed in all 10 paired primary tumour and PDCO sections, confirming the intestinal origin of these adenocarcinomas is maintained in culture." (PMID 31906589, 2020). "In spite of some conflicting studies, an overall experimental insight provided from previous studies is that CDX2 acts as tumor suppressor in GC31,32." (PMID 32704077, 2020). "The results showed that the expression level of CDX2 was significantly higher in adjacent tissues than in tumour tissues." (PMID 33109187, 2020). "H&E staining further showed that the tumor cells were decreased in response to treatment with CDX2 overexpression (p < 0.05)." (PMID 31938021, 2020).
tumor (continued). "Median OS in patients with BRAFmut or KRASmut and CDX2 expressed in tumor (both 21 months) was comparable to wild-type patients (27 months)." (PMID 32117703, 2020). "In the late stage of infection, the intestinalized gastric mucosa further progresses to dysplasia and GC, and CDX2 inhibits the invasion and growth of GC as it is a tumor suppressor gene." (PMID 33031021, 2020). "In different cancer types, the molecular mechanism by which CDX2 regulates tumor cell proliferation is intricate." (PMID 30631044, 2019). "We next performed a cell growth curve assay and an MTT assay to evaluate the tumor growth inhibition of CDX2 in vitro." (PMID 30631044, 2019). "In human CRC, a CDX2 reduction is inversely related to tumor grade, lymph node metastasis, tumor stage, and a poor prognosis." (PMID 30631044, 2019). "AM404 treatment showed slight/no reduction in PI staining followed by 6 days treatment period in tumour organoids, while differentiation markers CDX2 expression were significantly increased." (PMID 31906201, 2019). "This study was performed to evaluate the validity of CDX2 as a prognostic factor in patients with stage II/III CRC by using clinical tumor samples and to explore the specific miRNAs targeting CDX2." (PMID 31783700, 2019). "Immunostaining for CDX2 showed moderate staining in both tumor cells and normal colon epithelium cells, indicating well-differentiated tumors." (PMID 31242213, 2019). "Low CDX2 expression in tumours with a high stromal content identified patients with a particularly poor prognosis." (PMID 30847807, 2019). "In a number of tumours pronounced heterogeneity was found between the CDX2 staining in the overall tumour and the budding tumour cells." (PMID 30425348, 2018). "As in our cohort, LRP1 mRNA expression levels among the TCGA cohort were significantly lower in cases with right tumor location (p = 0.0003), MSI-H (p < 0.0001), BRAF mutation (p = 0.0015) CIMP-H (p < 0.0001) and low CDX2 expression (p < 0.0001)." (PMID 29507659, 2018). "Of the 235 tumours that were assessed for CDX2 status, the LNM rate was 46 per cent (17 of 37) in CDX2− tumours and 26·3 per cent (52 of 198) in CDX2+ tumours." (PMID 30511046, 2018). "This group was also characterised by reduced 5-year DFS compared to the patients with CDX2-positive tumours." (PMID 30425348, 2018). "They found that the prognostic impact of CDX2 depended on the MMR and BRAF mutational status of these tumours." (PMID 30511046, 2018). "The intestinal cell lineage is regulated by a transcriptional regulatory network where the tumor suppressor, Caudal homeobox 2 (CDX2) is considered to be an intestinal master transcription factor." (PMID 30087389, 2018). "There was a striking inverse correlation between CDX2 protein and percentage of methylation, which was limited to the serrated tumor group (r = − 0.7)." (PMID 30257705, 2018). "Focal loss of CDX2 expression in the budding tumour cells was detected in a subset of the patients (N = 80), with otherwise CDX2-positive or CDX2-moderate tumours." (PMID 30425348, 2018). "CDX2, a caudal-related homeobox gene, is an essential regulator of gene transcription and tumor suppression in gastrointestinal tract development and homeostasis." (PMID 30004434, 2018). "Although the tumours were morphologically similar, keratin/CDX2 expression was first shown to be highly specific and sensitive for distinguishing the two adenocarcinoma subtypes described in the present article." (PMID 29700411, 2018). "Considerable studies have confirmed that CDX2 is expressed not only in normal intestinal epithelial cells but also in different cancer cell types and functions as a tumour suppressor." (PMID 29179508, 2017). "In our study, we aimed to perform a more comprehensive quantitative assessment with a meta-analysis and to determine the value of CDX2 as a prognostic and predictive tumour biomarker." (PMID 29179508, 2017).
tumor (continued). "CDX2 plays a role in anterior-posterior patterning of the gut tube, impacts on differentiation of intestinal epithelial cells, and represents yet another tumor suppressor in colorectal carcinogenesis." (PMID 29155818, 2017). "Human serrated morphology CRCs and mouse Cdx2−/− BrafV600E-mutant tumor epithelium aberrantly expressed a number of gastric epithelial markers, including ANXA10, MUC5AC, and PDX1." (PMID 28072391, 2017). "For example, CDX2 is a TF with tumor suppressor functions that has been shown to be minimally expressed in CRC cell lines; the over-expression of CDX2 significantly inhibits the invasive ability of CRC cells." (PMID 28628609, 2017). "Of the SOX2 positive tumors, 73.9 % had less than 50 % CDX2 positive tumor cells, and of these 32.6 % had less than 5 % positive cells." (PMID 27411517, 2016). "The tumor origin was verified via strong immunopositivity for CDX2 (Caudal type homeobox 2, a marker for intestinal epithelial cells) in both cases and review of primary tumors." (PMID 27350555, 2016). "Our results in primary human tumours are supported by recent findings in the mouse small intestine, where CDX2 has been found to regulate HNF4α occupancy to control intestinal gene expression." (PMID 27677335, 2016). "Only by using pancreas as a CDX2 tissue control and focusing on the ability to demonstrate the small amount of CDX2 in cells of the ductal epithelium can a reliable demonstration of CDX2 be made in neoplasias with low expression levels." (PMID 26306713, 2016). "In this study, we analyzed the expression of four proteins from different signaling pathways (CDX2, p120ctn, c-Myc and Jagged1) in the progression of ND-BE to EAC, with the objective to increase the diagnostic accuracy of grading neoplasia in BE." (PMID 26926447, 2016). "This is not surprising, because the protein level of TNF-α is greatly elevated owing to induction of DSS in the CAC model, which deeply inhibits the expression of CDX2 in tumor cells and malignant transformed cells at the invasive front." (PMID 26910375, 2016). "We then examined the correlation between CDX2 expression and clinical and pathological parameters, such as gender, size of the tumor, lymph node metastasis, histological grade, depth of tumor invasion and metastasis in the GCC patient samples." (PMID 27384681, 2016). "The expression levels of Cdhr2 and Cdx2, which act as tumor suppressors, were more pronouncedly downregulated in tumors from Ifngr1−/−ApcMin/+ mice." (PMID 27286456, 2016). "Nuclear CDX2 expression was scored in tumor tissue as; less than 5 % positive cells, 5–50 % positive cells or, more than 50 % positive cells." (PMID 27411517, 2016). "Our data suggest that TGFβ signaling downregulates CDX2 expression, possibly early in tumor progression." (PMID 27221051, 2016). "Tumor growth was suppressed and tumor apoptosis was increased in nude mice when the CDX2 mRNA and protein were overexpressed via lentiviral vector-mediated overexpression of CDX2." (PMID 25738600, 2015). "Cdx2 is a transcription factor with tumor-suppressor activity in the intestine, possibly mediated by inhibitory effects on cell proliferation, but it is also reported to have tumorigenic activity by repressing cell apoptosis." (PMID 26460825, 2015). "A nude mouse subcutaneously-transplanted tumor model was established by inoculating the nude mice with the pEGFP-C1-CDX2 cells, and the effects of overexpression of CDX2 on transplanted tumor growth in the LoVo cells were observed." (PMID 26005051, 2015). "MTT assays were used to measure the effects of CDX2 on tumor cell proliferation within 72 h, as well as on the cell cycle and apoptosis." (PMID 26005051, 2015). "In the present study, protein expression of CDX2 was observed in the tumor tissues following inoculation with the pEGFP-C1-CDX2 cells." (PMID 26005051, 2015). "The tumor weight in the pEGFP C1 CDX2 group was significnatly lighter than the other two groups (*P<0.05)." (PMID 26005051, 2015).
tumor (continued). "The present study revealed that the overexpression of CDX2 inhibited the proliferation of LoVo tumor cells in vivo." (PMID 26005051, 2015). "The tumor cells were positive with the epithelial markers pancytokeratine and Cam 5.2, calretinin, and CDX-2 (weak) in accordance with the diagnosis." (PMID 25338547, 2014). "SOX2 and CDX2 expression were crossed with clinicopathological and follow-up data to determine their impact on tumor behavior and outcome." (PMID 25300947, 2014). "miR-9 has been shown to target fibroblast growth factor receptor 1 (FGFR1) and CDK6 in ALL and caudal-type homeobox 2 (CDX2) in GC, suggesting a tumor-suppressive function." (PMID 24348513, 2013). "The AUC value for Cdx2 expression in tumor was 0.87 indicating 87% accuracy for discriminating MMR-proficient and – deficient cancers." (PMID 24130965, 2013). "Numerous studies indicate that CDX2 performs a tumor suppressor role in human colorectal carcinogenesis." (PMID 23408490, 2013). "Baba and colleagues showed similar results of Cdx2 loss with more advanced TNM stage, higher tumor grade, mucinous, or signet ring cell histology." (PMID 24130965, 2013). "We report a novel mechanism of ephrin-A1 mediated attenuation of NSCLC tumor growth due to down regulation of claudin-2 and induction of tumor suppressor gene cdx-2." (PMID 22824143, 2012). "We demonstrate that activation of receptor EphA2 with ephrin-A1 induced cdx-2 expression and inhibited tumor formation." (PMID 22824143, 2012). "Immunohistochemistry showed strong positivity with CDX2, confirming that the origin of the tumor was the colon." (PMID 22330123, 2012). "The over expression of cdx-2 by vector pcMV-cdx-2 resulted in downregulation of claudin-2 and attenuation of cell proliferation and tumor growth on matrigels." (PMID 22824143, 2012). "In this study, we attempted to understand the underlying mechanisms by which EphA2 over expression leads to enhanced or irregular claudin-2 expression via cdx-2 modulation and promote tumor growth in NSCLC cells." (PMID 22824143, 2012). "The reduced expression of SATB2 in MSI tumours is consistent with studies on other markers of colorectal lineage, for example, CDX2 and CK20." (PMID 22333599, 2012). "Qualitatively, focal and weak CDX2 expression in a given tumor favors extra-intestinal origin whereas uniform intense expression favors intestinal origin." (PMID 22268990, 2012). "The novel finding of our present study is that receptor EphA2 mediated the enhanced induction of functionally altered claudin-2 via down-regulation of tumor suppressor gene expression cdx-2 in NSCLC cells." (PMID 22824143, 2012). "The expression of CDX2 varied according to histological grade, with 100% of well-differentiated tumours and 58% of poorly differentiated tumours expressing CDX2." (PMID 19935793, 2010). "The phenotypes CK7+ MUC4+ and CK7+ CDX2− optimally classified tumours as IHC pancreatobiliary, and the phenotypes CK7− and MUC4− CDX2+ optimally classified tumours as IHC intestinal." (PMID 19236510, 2009). "CDX2 immunostain highlighted the tumor glands and single cells, supporting the diagnosis of LGCC." (PMID 41853395, 2026). "Caudal type homeobox 2 (CDX2) is an intestine-specific transcription factor that serves as a diagnostic marker of enteric differentiation and may also reflect tumor behavior and therapeutic susceptibility." (PMID 41744890, 2026). "Conversely, reduced expression of CDX2, mediated by promoter hypermethylation, has been linked to a higher risk of CRC development and progression, as the silencing of this gene facilitates tumor growth." (PMID 40740242, 2025). "In our case, the tumor was positive for CDX2, CK20, and SATB2." (PMID 41328080, 2025). "Of the LG tumours 23/24 (95.8%) stained positively for CDX2 (e.g., HT55, IS2, SW1116 and SW948)." (PMID 40473896, 2025). "In contrast, tumor cells were heterogeneously positive for CDX2 and HTR2B immunostaining." (PMID 41034989, 2025).